CSF3 (colony stimulating factor 3)
Diseases named in the same sentence as CSF3 in open-access papers (continued):
Sharing a sentence is not in itself a finding about the gene and the disease.
cancer (continued). "Further analysis by treatment revealed that both Il6 and Csf3 gene expression increased in Fibro/CAFs 1 after chemotherapy, while there was a marginal decrease in expression of Il6 in cancer cells (D2.0R 2) with no Csf3 expression." (PMID 37699010, 2023). "Therefore, we focused on upregulated secretome genes that included several known cachexia mediators described in pan-cancer and NSCLC, such as IL6, IFNG, LIF, CCL2, and CSF3." (PMID 36774484, 2023). "Interestingly, both cancers showed significant correlations of formyl peptide receptors FPR1 and FPR2 with CSF3 and CSF3R." (PMID 33606788, 2021).
bacterial infection (69 papers, 2004 to 2025). "The heat map showed that the gene expression levels of 62 DEGs were upregulated and that some of these genes, such as IL-6, IL-1β, CCL2, CXCL2, CXCL8, and CSF3, are closely associated with host defense responses to bacterial infection." (PMID 31737164, 2019). "Chronic skin inflammation worsened in Peds1-deficient larvae but was mitigated by exogenous plasmalogen, which also alleviated hyper-susceptibility to bacterial infection, as did pharmacological inhibition of caspase-3 and colony-stimulating factor 3-induced myelopoiesis." (PMID 39209813, 2024). "Relatively low expression of Csf3 might result in the predisposition of Hexa−/−Neu3−/− mice to bacterial infection which requires further investigation." (PMID 32951593, 2020). "In response to bacterial infections and cell-mediated immune responses, the production of Csf3 increases dramatically." (PMID 34457033, 2021). "Amplification of leukocyte numbers during zebrafish bacterial infection has been shown to depend on signalling through the Csf3-Csf3r pathway, while both Csf3 and Interleukin-6 are known to be important in the response to yeast infection in mammalian systems." (PMID 29883484, 2018).
inflammation (18 papers, 2014 to 2024). Aberrant reaction of the microcirculation characterized by movement of fluid and leukocytes from the blood into extravascular tissues. "To define possible mechanisms underlying lung damage in DSS-treated TCRδ-/- mice, we analyzed the expression of genes encoding cytokines and chemokines known to contribute to predominately neutrophilic lung inflammation including Csf3, Cxcl2, Il17a, and the monocyte chemoattractant Ccl2." (PMID 37063825, 2023). "CSF3 stimulates the activity of neutrophils, suggesting that EVs released during T17 inflammation may promote neutrophilic airway inflammation." (PMID 32560723, 2020). "CSF3 may contribute to lung inflammation, as it increases neutrophil chemotactic activity." (PMID 26485688, 2015). "Specifically, severe pyuria and bladder inflammation with elevated serum interleukin-5 (IL-5) and serum and urine IL-6, the neutrophil chemokine CXCL1, and granulocyte colony-stimulating factor (G-CSF or CSF3) at 24 hpi are predictive of chronic infection." (PMID 26125048, 2014).
infectious disease (10 papers, 2011 to 2025). A disorder directly resulting from the presence and activity of a microbial, viral, or parasitic agent in humans. "The metabolic function of CSF3 is related to immunity or infectious diseases, and hsa04657 (IL-17 signaling pathway) is related to IL-17." (PMID 32273901, 2020).
adenocarcinoma (9 papers, 2007 to 2024). A common cancer characterized by the presence of malignant glandular cells. "Among these, 13 hub genes were identified, with colony-stimulating factor 3 (CSF3) uniquely associated with post-progression survival (PPS) in adenocarcinoma patients undergoing chemotherapy." (PMID 39727962, 2024). "Prognostic analysis using the Kaplan–Meier Plotter revealed that higher expression of CSF3 and CCRL2, as well as lower expression of IL1A, were significantly associated with prolonged PPS in adenocarcinoma patients undergoing chemotherapy." (PMID 39727962, 2024). "Additionally, elevated expression of CSF3 correlated with the PPS of adenocarcinoma patients receiving chemotherapy." (PMID 39727962, 2024).
CSF3 also shares sentences with these, for which no sentence is quoted: leukemia (101 papers); leukopenia (89); Thrombocytopenia (87); lymphoma (84); leukocytosis (79); myocardial infarction (70); hematological malignancies (56); pneumonia (55); agranulocytosis (51); diabetes (49); myelodysplastic syndrome (46); non-Hodgkin lymphoma (45); ischemic stroke (33); cervical carcinoma (31); acute myocardial infarction (30); Cerebral ischemia (30); infertile (30); acute GVHD (29); Arthritis (27); colon carcinoma (27); influenza (27); acute respiratory distress syndrome (26); Cirrhosis (26); Obesity (26); fungal infections (24); gastric cancer (24); vasculitis (24); lymphopenia (23); graft versus host disease (22); mucositis (22).
A further 700 diseases each share a sentence with CSF3 in 22 papers or fewer.